HSPA5 (heat shock protein family A (Hsp70) member 5)
Diseases named in the same sentence as HSPA5 in open-access papers (continued):
Sharing a sentence is not in itself a finding about the gene and the disease.
cancer (continued). "The Cancer Genome Atlas (TCGA) database of HNSCC patients was used to examine the expression of up-regulated genes, and CALR, HSPA5, and TRIB3 were found to be highly expressed relative to solid normal tissue in cancer and the survival rate was reduced in patients with high expression." (PMID 34580365, 2021). "The inhibition of PCNA, cyclin D1 and HSPA5 expression by this combination is encouraging as a means to preferentially target cancer cells without affecting normal cells." (PMID 30218018, 2018). "UPR effectors, including ERN1 (IRE1α), ATF6, and PERK (EIF2AK3), dissociate from HSPA5 (GRP78) and activate their respective canonical targets (XBP1s, ATF6α, and ATF4); subsequently trigger transcriptional reprogramming that promotes the survival of cancer cells under ER stress." (PMID 40821803, 2025). "HSPA5, RCN1, CLGN, and TXD15 need to be validated using an assay method compatible with use in a central lab (e.g., ELISA) in a large prospective study of patients with advanced-stage cancer before these proteins can be used to guide anticoagulation prophylaxis." (PMID 37651191, 2023). "We found that mRNA expression of HSPA5 was the highest, followed by FURIN and CTSL in the majority of the tumor tissues, and ACE2 expression was the lowest, demonstrating that CTSL might facilitate tumorigenesis and SARS-Cov-2 entry in most cancers." (PMID 35414771, 2022). "Altogether, those results indicated that the HSPA5 might play more important roles for SARS-Cov-2 entry in most of the cancer patients through different malignant tissues, or be prone to attack in most of the different types of cancer patients." (PMID 33767597, 2021). "HspA4 (a non-canonical Hsp70 member), HspA5 (an Hsp of the endoplasmic reticulum (ER) also referred to as Grp78), and HspA9 (a mitochondrial Hsp also referred to as Grp75) have been demonstrated to activate Akt in cancer models." (PMID 34222357, 2021). "Likewise, targeting HSPA5 using small molecule drugs has proven to induce endoplasmic reticulum stress and apoptosis selectively in cancer cells, and not normal cells." (PMID 30218018, 2018). "HSPA5 levels increased in the absence of NRF3, thereby promoting cancer cell survival and migration." (PMID 37807968, 2023). "However, the remaining eight cancer-specific DESPGs of GLB1, HSPA5, PDIA3, GNRH1, IFNGR2 ADAM9, TPST2, and TAC4) were not reported in any researches, which could be potential novel prognostic biomarkers in corresponding tumors." (PMID 31824949, 2019).
tumor (595 papers, 2005 to 2026). "These analyses revealeda significant upregulation of ER chaperone mRNA expression in aHGGrelative to aLGG and aNNB that was associated with tumor aggressiveness and patientsurvival for HSPA5, HSP90B1, P4HB, and SERPINH1." (PMID 41287960, 2026). "Here, the results of our study demonstrate that HSPA5 is elevated in BCa tissues and significantly associated with tumor progression and poor prognosis in BCa patients." (PMID 36982218, 2023). "Among highly perturbed gene pairs across multiple tumor types are HSPA5, CXXC1, SERP1, SCH1, and PDIA6, which encode proteins that confer resistance to various forms of stress." (PMID 35237269, 2022). "Differential expression analysis of the hyperexpanded clones compared to all other clones revealed an elevated expression of tumor promoting factors/oncogenes (HSPA5, PDIA4, MANF, PPIB) and a gene associated with malignant B cell clones (CD63)." (PMID 36153593, 2022). "HSPA5 is a molecular chaperone expressed primarily in the endoplasmic reticulum and is closely associated with tumor progression and poor prognosis." (PMID 35652069, 2022). "As the most significant CALU-associated gene, HSPA5 has been demonstrated to play a vital role in tumor cell’s ferroptosis resistance through interaction with GPX4, a critical gene for ferroptosis." (PMID 34150647, 2021). "HSPA5 was found highly expressed in all subtypes, and especially upregulated in Basal tumours in our study, and has been associated with endoplasmic reticulum stress response (ERSR), inhibition of apoptosis and autophagy in several studies." (PMID 29954368, 2018). "HSPA5 has different effects on cell transformation and associates with aggressive growth and invasive properties in various tumor models." (PMID 25301734, 2014). "Excess dietary iron in tumor tissues was also associated with significant changes (generally, increases; p ≤ 0.05) in proteins involved in modulating cell protein integrity (HSPA5, HSPA9, ITGB1, PSMA4, DPP7, and PEPD), cell mobility and growth (CAPZB), and immunologic factors (FCGBP)." (PMID 38732562, 2024). "Clinically, PAT-SM6 is the only HSPA5 inhibitor in phase I clinical trials for tumor therapy, but this trial was terminated due to limited clinical benefits." (PMID 41301006, 2025). "To provide more convincing evidence unraveling that SBSPON is involved with drug resistance of tumor cells through binding to HSPA5 under ER stress, we performed Co-Immunoprecipitation between HSPA5 and PERK." (PMID 40765821, 2025). "Although it predominantly resides in the ER, HSPA5 can translocate to the tumor cell surface under stress conditions, a phenomenon rarely observed in normal cells." (PMID 40597436, 2025). "Analysis of GEO databases showed HSPA5 was upregulated in EAC tumor tissues compared to the normal adjacent tissues." (PMID 40603306, 2025). "Several studies shown that HSPA5 enhanced tumor cell survival and conferred drug resistance during ERS." (PMID 40255561, 2025). "In such cases, upon targeting with systemic monoclonal antibody therapies, cs-HSPA5 blockade was shown to enhance the efficacy of radiotherapy in tumor models." (PMID 41301006, 2025). "Further analysis showed that HSPA5 was significantly expressed in tumor tissues and co-expressed with Rab27A protein." (PMID 38521810, 2024). "Mechanistically, the tumor‐suppressive effect of NRF3 involves HSPA5, a key regulator of the unfolded protein response, which we identified as a potential NRF3 interactor." (PMID 37807968, 2023). "Further analysis of the shared 61 proteins revealed that there were a large number of tumor-related proteins, such as HSPA5, HNRNPH1, HSPA8, TGM3, and SERPINB12." (PMID 37715221, 2023). "Here we show that NRF3 acts as a potent tumor‐suppressing protein in the skin by controlling the unfolded protein response regulator HSPA5, which we identified as promising target for the treatment of NMSC." (PMID 37807968, 2023).
tumor (continued). "We found that the tumour volumes and weight in the sh-HSPA5 groups were smaller than that in the control group." (PMID 36982218, 2023). "A series of studies have demonstrated that GRP78/HSPA5 is anti-apoptotic and has a critical cytoprotective role in oncogenesis (protects tumor cells from ER stress)." (PMID 36557005, 2022). "Radiotherapy combined with the treatment of anti-HSPA5 resulted in significant tumor growth delay, and enhanced radiotherapy efficacy in glioblastoma and non-small cell lung cancer." (PMID 35342334, 2022). "The heat shock 70 kDa protein 5 (HSPA5) has recently been discovered to have an important function in tumor growth." (PMID 36193502, 2022). "The study has indicated that HSPA5 inhibition is a promising method for inducing the endoplasmic reticulum stress, autophagy, and apoptosis of tumor cells." (PMID 36438897, 2022). "Studies have shown that cell surface HSPA5 is an upstream regulator of the PI3K/AKT signalling pathway by targeting HSPA5 to inhibit tumor progression." (PMID 35342334, 2022). "From these results, we can conclude that HSPA5 is highly expressed in BC tumor tissues, and the highly expressed HSPA5 has a shorter survival time than the lowly expressed HSPA5." (PMID 36193502, 2022). "In conclusion, the level of HSPA5 in BC tumor tissues was significantly higher, and its high expression was related to poor PFS and PPS in BC patients." (PMID 36193502, 2022). "The endoplasmic reticulum chaperone BiP (also known as GRP-78 or HSPA5) maintains protein folding to allow cell proliferation and survival and has been implicated in carcinogenesis, tumor progression, and therapy resistance." (PMID 36547124, 2022). "HSPA5 is the master regulator of UPR and is associated with tumor progression, tumor size, and poor prognosis." (PMID 34580365, 2021). "The relationship between HSPA5 expression levels of different specific tumor types and the disease severity should further be explored." (PMID 33767597, 2021). "In summary, our analyses showed that HSPA5 is expressed in almost all the normal tissues and elevated expression in tumor tissues." (PMID 33767597, 2021). "In fact, high levels of HSPA5 expression have been correlated with increased malignancy and radioresistance in different tumor types." (PMID 33902430, 2021). "According to data mining and patient tissue analysis, the expression of HSPA5 is positively correlated with the malignant degree of tumor." (PMID 34026352, 2021). "Due to the harsh living environment of tumor cells, most malignant tumor cells themselves have slight chronic ER stress, and ER chaperone HSPA5 is often highly expressed in tumor cells." (PMID 34070303, 2021). "Four heat shock proteins (Hspa5, Hsp90ab1, Hspa8 and Hsp90aa1) were included in the top candidate list and Hsp90ab1 was predicted to be one of the most influential tumor suppressors, as well as calreticulin (Calr) and peptidylprolyl isomerase B (Ppib)." (PMID 33859739, 2021). "Blocking TGFβ-receptor signaling with SB-431541 significantly reduced mRNA-expression of ER-stress markers DDIT3, spliced XBP1 and HSPA5 in stellate cells co-cultured with tumor cells using transwells." (PMID 33103995, 2020). "An emerging target that plays a critical role in tumor cell survival, tumor progression, and drug resistance is the 78-kDa glucose-regulated protein (GRP78), also known as the immunoglobulin binding protein (BiP) and heat shock protein A5 (HSPA5)." (PMID 30038714, 2018). "GRP78/BiP/HSPA5 is a major chaperone in the endoplasmic reticulum (ER), which regulates a number of biological functions including tumor proliferation and metastasis as well as chemo/radioresistance." (PMID 29212198, 2017). "Next, we used the established stable transfectants to further investigate the effects of HSPA5 on E1A-mediated anti-tumor activity in a xenograft tumor model." (PMID 25301734, 2014).
tumor (continued). "HSPA5 exhibits oncogenic activities by promoting tumor proliferation, survival, metastasis, and drug resistance and is associated with malignancy and poor prognosis." (PMID 25301734, 2014). "HSPA5 overexpression has been reported in many tumor types, including lung, breast, prostate, colon, stomach and liver." (PMID 25301734, 2014). "Our findings point out the Ying-Yang regulation of two different post-translational modifications (ubiquitination and acetylation) of HSPA5 in tumor metastasis." (PMID 25301734, 2014). "Based on our study, E1A-mediated GP78 E3 ubiquitin ligase activity acts as a tumor suppressor through HSPA5 regulation." (PMID 25301734, 2014). "Whereas the research on the role of HSPA5 in non-neoplastic diseases was relatively scarce." (PMID 40255561, 2025). "Additionally, HSPA5 contributes to tumor cell survival and chemoresistance by facilitating the correction of misfolded proteins and enabling recovery from ER stress, making it an attractive target for therapeutic inhibition in cancer cells." (PMID 40597436, 2025). "MRNA expression level of BSG was the highest, followed by HSPA5 in most tumor and normal tissues." (PMID 38484369, 2024). "While this may simply reflect the assistance of HSPA5 in the folding of NRF3, our follow‐up data revealed a functional role of HSPA5 in the tumor‐suppressive effect of NRF3 in keratinocytes, and HSPA5 protein levels increased upon loss of NRF3." (PMID 37807968, 2023). "The biological effects of HSPA5 on tumor cells and the underlying mechanisms have not been clarified." (PMID 36982218, 2023). "Moreover, the IHC results indicated that Ki-67 expression was low in the sh-HSPA5 groups, which demonstrated that downregulation of HSPA5 inhibited tumour growth in vivo." (PMID 36982218, 2023). "Therefore, the high expression of HSPA5 in tumor cells has a certain protective effect on the growth of tumor cells." (PMID 36193502, 2022). "In addition, inhibition of autophagy overcame HSPA5-mediated resistance, and the simultaneous knockdown of HSPA5 and Beclin-1 restored sensitivity in resistant tumor cells." (PMID 33902430, 2021). "M2 macrophages could elevate HSPA5 expression to trigger an inflammatory response, and thus facilitating tumor metastasis." (PMID 34712697, 2021). "Our investigations further demonstrated that the anti-tumor properties of HSPA5 inhibition as well as small molecule-mediated PERK activation may also apply to the HER2+-BC." (PMID 34007022, 2021). "However, in tumor cells, HSPA5 is not only expressed in the ER but also at an elevated level on the cell surface of many tumors." (PMID 27034162, 2016). "In addition, Western blot analysis revealed that protein levels of FOXM1 and HSPA5 were upregulated in tumor samples relative to normal tissues." (PMID 27034162, 2016). "Therefore, HSPA5 has some potential as a novel therapeutic target for both anti-tumor and anti-angiogenesis activity." (PMID 27571357, 2016). "HSPA5 knockdown also inhibits tumor cell metastasis in vitro and in vivo." (PMID 25301734, 2014). "Interestingly, our in vivo results suggest that GP78 negatively regulates tumor metastasis and tumor growth in response to E1A through the HSPA5 ubiquitination." (PMID 25301734, 2014). "In a previous study, we could demonstrate that PAT-SM6 targets a tumour specific variant of the heat shock protein GRP78 (BIP, HSPA5)." (PMID 23667612, 2013). "In colorectal cancer patients, not only was there differential expressions of PERK and HSPA5 in tumor and metastatic tissues but also single nucleotide polymorphisms were predicted to contribute to genetic variants that may influence the susceptibility of targeted UPR agents." (PMID 41301006, 2025). "The predictive utility of HSPA5 may vary with tumor type or specific subtypes." (PMID 39323470, 2024). "Recent studies report that HSPA5 could influence the growth of tumours by controlling ferroptosis." (PMID 36291587, 2022).
tumor (continued). "Critically, the 13 proteostasis gene set lacked any strong association with aggressive tumor types with only heat shock 70 kDa protein 5 (HSPA5) common in 3 datasets, further supporting that its predictive value would be defined predominately by molecular influences affecting RAI therapy." (PMID 34520744, 2022). "Thus, HSPA5 has been proposed as an emerging therapeutic target in anti-tumor strategies." (PMID 33902430, 2021). "HSPA5 is a key regulator of the UPR and has significant implications in cell survival and tumor progression, while reports on the roles of DNAJC10 in tumorigenesis are limited." (PMID 40765821, 2025). "Conversely, genetic or pharmacological inhibition of HSPA5 disrupts this compensatory pathway, significantly enhancing DHA-induced tumor cell demise." (PMID 40452834, 2025). "The top 5 overexpressed proteins in tumor compared to NT (ranked according to the log2(FC) T vs CT) included SFRP2, KDM5A, CMTM5, HSPA5 and FN1." (PMID 39681068, 2024). "Heat Shock Protein Family A Member 5 (HSPA5) is a member of the HSP70 protein family that is involved in regulation of EMT process and tumor metastasis." (PMID 38730433, 2024). "Our findings reveal that tumor cells in relapsed patient exhibit higher expression levels of HSP90B1 and HSPA5, and demonstrate significantly enriched pathways regarding endoplasmic reticulum stress and unfolded protein response." (PMID 38035111, 2023). "In summary, we identified a tumor‐suppressive function of NRF3 in the skin, which involves its interaction with the UPR regulator HSPA5." (PMID 37807968, 2023). "Given the pathogenic roles of MSI2 in tumor progression, as well as the protective roles of HSPs in ferroptosis, we demonstrated that MSI2 could regulate multiple HSPs to repress ferroptosis, especially the ferroptosis suppressor genes HSPB1 and HSPA5, as evidenced by previous studies." (PMID 38041016, 2023). "Meanwhile, animal tumor protein Western Blot experiment showed a decrease in LC3BI/LC3BII, which further confirmed the lower expression of HSPA5 and autophagy in tumors after LV-miR-infection." (PMID 35342334, 2022). "Corresponding immunofluorescence results showed that the expressions of HSPA5 and LC3B were increased in tumor tissues, especially in radioresistive tissues." (PMID 35342334, 2022). "The corresponding heat map further proved that HSP90B1 was positively correlated with the six genes (HSPA5, PDIA3, MANF, PDIA4, CALR, and PDIA6) in various tumours." (PMID 36291587, 2022). "Expectedly, HSPA4 overexpression increased the levels of HSPA4, HSPA5, CHOP, SDC-1, SDCBP-1, SOX4, FZD4, and β-catenin in tumor tissues, but 4-PBA inhibited the generation of these proteins." (PMID 35442158, 2022). "Among highly perturbed gene pairs across multiple tumor types, we noted CXXC1, HSPA5, GSK3A, SERP1, PDIA6, FKBP14, and SCH1, which showed multiple co‐expression changes." (PMID 34698427, 2021). "Out of the twenty‐three tumor types with available matched normal samples in TCGA, all except three (THCA, KICH, and KIRP) showed greater HSPA5 expression in tumors, and thirteen of these showed statistical significance (FDR < 0.05)." (PMID 34698427, 2021). "We found that HSPA5 and PSME2 were significantly upregulated whereas HLA-F was significantly downregulated in tumor tissues compared with normal tissue (p < 0.0001)." (PMID 34257557, 2021). "The targeting of STAT3 and HSPA5 with BBI608 and HA15, respectively, significantly increased apoptosis and diminished tumorsphere formation in colorectal HCT116 and HT29 tumor cells." (PMID 33023006, 2020). "mRNA Log2 expression comparisons between non-tumor control and GBM specimen, respectively, were as follows: HSPA5, 10.38 ± 0.01 vs. 11.56 ± 0.02, p < 0.001; HSP90B1, 8.36 ± 0.08 vs. 8.98 ± 0.02, p < 0.001." (PMID 30709011, 2019).